RHOBTB2 (Rho related BTB domain containing 2)
Diseases named in the same sentence as RHOBTB2 in open-access papers:
RHOBTB2 is named in the same sentence as 43 diseases in open-access papers, as found by Europe PMC text mining. Sharing a sentence is not in itself a finding about the gene and the disease. The quoted sentences say what the papers report.
breast carcinoma (15 papers, 2008 to 2025). "In fact, methylation of RHOBTB2 and other genes in peripheral blood is a potential epigenetic marker for predicting the risk of breast cancer development." (PMID 27314390, 2016). "Additionally, RhoBTB2, a candidate tumor suppressor, has been implicated in various cancers, such as breast cancer and lung cancer." (PMID 34124157, 2021). "RHOBTB2 has been implicated as a tumour suppressor gene associated with breast cancer survival." (PMID 29423119, 2018). "Moreover, deletions and loss-of-function variants in RHOBTB2 were detected in nearly 10% of breast cancer samples, suggesting that these variants may lead to the loss of tumor-suppressor activity and the initiation of cancerous tumor formation." (PMID 39736890, 2024). "The cancer susceptibility gene deleted in breast cancer (Dcb2), known as Rho-related BTB domain containing 2 (Rohbtb2), mapped closed to the Lpl gene which may also be affected by Lpl deletion and could therefore exert a combined impact on promoting carcinogenesis." (PMID 35388653, 2022). "RHOBTB2 (also called deleted in breast cancer 2 (DBC2)) has been reported as a gene homozygously deleted in breast cancer samples." (PMID 34074803, 2021). "Many studies have reported downregulation of RhoBTB2 expression in breast cancer, most commonly due to methylation of the RhoBTB2 promoter." (PMID 28219369, 2017). "Hamaguchi and colleagues identified RhoBTB2 in a representational difference analysis screen for novel tumor suppressor genes in breast cancer, and gave it the alternative name DBC2 (deleted in breast cancer 2)." (PMID 28219369, 2017). "We examined the relative expression of RhoBTB1 and RhoBTB2 in a selection of human breast cancer cell lines (MDA-MB-231, T47D, MCF7) in comparison to two well-characterized normal human mammary epithelial cell lines – MCF10A and HMT-3522 S1." (PMID 28219369, 2017). "The expression of the wild-type tumor-suppressor gene DBC2 (Deleted-in-Breast Cancer 2, a.k.a RhoBTB2) is suppressed in many cancers, in addition to breast cancer." (PMID 24608665, 2014). "The molecular mechanism behind SNP rs992531 and poor breast cancer outcome in ER-positive cases may therefore involve altered RHOBTB2 expression and its interplay with cyclin D1 and the oestrogen receptor." (PMID 29423119, 2018). "The effects of RhoBTB2 on cell proliferation were observed in early studies where overexpression of the protein in the breast cancer cell line T-47D (a cell line that lacks RHOBTB2 transcripts) effectively suppressed cell growth and increased the apoptotic ratio in vitro." (PMID 27314390, 2016). "Furthermore, patients with RHOBTB2-negative breast cancer have been linked to poor prognosis, and RHOBTB2 silencing is an independent risk factor for breast cancer." (PMID 32316112, 2020). "Previously, we showed that miR-5088-5p is more highly expressed in breast cancer patients and increases malignancy and metastasis via downregulating target DBC2 (Deleted in Breast Cancer 2; RHOBTB2)." (PMID 36632615, 2023). "Interest in RhoBTB arose when RHOBTB2 (also called DBC2, deleted in breast cancer 2), was identified as the gene homozygously deleted in breast cancer samples and was proposed as a candidate tumor suppressor gene." (PMID 27314390, 2016). "DBC2 inactivation, also known as RHOBTB2, is a tumor suppressor gene involved in breast cancer development." (PMID 23626933, 2012). "Downregulation of RHOBTB2 and RHOBTB3 is common in breast cancer." (PMID 29423119, 2018).
Epileptic encephalopathy (7 papers, 2020 to 2025). A condition in which epileptiform abnormalities are believed to contribute to the progressive disturbance in cerebral function. "RHOBTB2 has been identified in prior studies as a potential candidate 8p driver gene due to its association with epileptic encephalopathy and other phenotypes overlapping with 8p syndrome." (PMID 40894639, 2025). "Here we report a case of developmental and epileptic encephalopathy related to RHOBTB2 gene mutation in a ten-month old infant in French Guiana." (PMID 35315256, 2022). "Missense variants in Rhobtb2 have been reported to cause a developmental and epileptic encephalopathy in humans, and altered levels triggering neurological defects in drosophila." (PMID 32392183, 2020). "Mutations in another CUL3-associated protein, rho-related BTB domain-containing protein 2 (RHOBTB2), have been found in several patients with epileptic encephalopathy." (PMID 35327449, 2022).
epilepsy (5 papers, 2020 to 2024). A brain disorder characterized by episodes of abnormally increased neuronal discharge resulting in transient episodes of sensory or motor neurological dysfunction, or psychic dysfunction. "In addition, a growing number of genes initially linked to other neurological phenotypes, such as developmental delay, epilepsy, or ataxia, are now recognized to cause prominent dystonia, occasionally in an isolated fashion (e.g., GNAO1, GNB1, SCN8A, RHOBTB2, and COQ8A)." (PMID 36705216, 2022). "Developmental regression, autism, and epilepsy can also be seen in disorders of ion channels (i.e., Dravet syndrome), impairments of receptor expression (i.e., GRIN1), transcription factors (i.e., MEF2C), axonal guidance (i.e., NTNG1), and ubiquination (i.e., RHOBTB2)." (PMID 37511662, 2023).
breast tumor (4 papers, 2005 to 2017). "The RhoBTB2/DBC2 gene undergoes homologous deletion in a relatively small number of breast tumor samples; however, RhoBTB2 expression is silenced at high frequency (approximately 50%) in breast and lung tumors." (PMID 28219369, 2017). "An additional contributing gene Deleted-in-Breast Cancer 2 (DBC2, a.k.a RhoBTB2) was identified in a region of human chromosome 8p21 that is homologously deleted in 3.5% of breast tumors." (PMID 24608665, 2014).
developmental and epileptic encephalopathy (3 papers, 2022 to 2024). An epilepsy associated with developmental impairment that may be due to either the underlying etiology or the superimposed epileptic activity, or both. "Alternatively, variants in RHOBTB2 that lead to elevated RHOBTB2 levels are associated with developmental and epileptic encephalopathies (DEE)." (PMID 39736890, 2024). "Beyond its cancer-related role, RHOBTB2 is implicated in rare neurodevelopmental disorders, specifically RHOBTB2-related disorders, recognized in 2018 as a subtype of developmental and epileptic encephalopathies (DEE)." (PMID 39736890, 2024). "The publication of cases of such a rare form of developmental and epileptic encephalopathy will eventually allow us to better understand the mechanism by which RHOBTB2 misregulation could induce severe and atypical neurological disorders." (PMID 35315256, 2022). "However, it remains unknown how increased levels of RHOBTB2 in neurons lead to developmental epileptic encephalopathy (DEE)." (PMID 39736890, 2024). "Within the cohort of patients experiencing developmental and epileptic encephalopathy (DEE), WES has revealed genetic variants in novel genes (FGF12, GABBR1, GABBR2, ITPA, KAT6A, PTPN23, RHOBTB2, SATB2) and candidate epilepsy-associated genes (CAMTA1, FAT3, GABRA6, HUWE1, PTCHD1)." (PMID 39523358, 2024). "RHOBTB2-related disorders were first characterized as a severe subtype type of NDD, known as developmental and epileptic encephalopathy (DEE)." (PMID 39736890, 2024).
acute promyelocytic leukemia (1 paper, 2021). An aggressive form of acute myeloid leukemia (AML), characterized by arrest of leukocyte differentiation at the promyelocyte stage, due to a specific chromosomal translocation t(15;17) in myeloid cells. "Moreover, RHOBTB2 expression was increased in non-acute promyelocytic leukemia (APL) subtypes, patients without FLT3 mutation and PML/RAR fusion, and imparted a positive correlation with the expression of FLT3, FHL1, and RUNXs." (PMID 34074803, 2021). "The box plots showed that RHOBTB2 was remarkably increased in FAB subtypes M0, M1, M2, M4, and M5 compared to that in M3 (also known as acute promyelocytic leukemia (APL)), which has a higher degree of differentiation (P < 0.001 for M0 vs. M3, M1 vs. M3, M2 vs. M3, M4 vs. M3 and M5 vs. M3)." (PMID 34074803, 2021).
asthma (1 paper, 2023). "Moreover, the differentially co-expressed genes, both up- and down-regulated in EA, were previously linked to asthma in the genome- (e.g., MRPL14, ASB3, RHOBTB2) and epigenome-wide (e.g., CLC, EPS15, GPI, SRCRB4D, STRN4) association studies." (PMID 36835202, 2023). "Among the differentially co-expressed genes, eight were previously linked to asthma in genome- (MRPL14, ASB3, RHOBTB2) and epigenome-wide (CLC, EPS15, GPI, SSCRB4, STRN4) association studies and five were mentioned in the literature in the context of asthma (SLC19A1, MAEA, CLC, ATP1B1, and RECK)." (PMID 36835202, 2023).
leukemia (1 paper, 2021). A malignant (clonal) hematologic disorder, involving hematopoietic stem cells and characterized by the presence of primitive or atypical myeloid or lymphoid cells in the bone marrow and the blood. "Consistently, three datasets indicated increased RHOBTB2 expression; six datasets and five datasets showed reduced RHOBTB1 and RHOBTB3 expression, respectively, in leukemia compared to normal samples in the ONCOMINE database." (PMID 34074803, 2021). "E2F1 may promote the transcription of RHOBTB2 during mitosis, which affects the cell cycle and boosts the proliferation of AML leukemia cells." (PMID 34074803, 2021). "Therefore, the results above suggest that both RHOBTB2 and RHOBTB3 may be potential prognostic factors for patients with leukemia, and RHOBTB2 showed better prognostic performance." (PMID 34074803, 2021).
malnutrition (1 paper, 2020). Inadequate nutrition resulting from poor diet, malabsorption, or abnormal nutrient distribution. "And we further identified Cebpa, a transcription regulatory factor of Rhobtb2, was differentially expressed after exposure to prenatal malnutrition." (PMID 32392183, 2020).
melanoma (1 paper, 2017). A malignant, usually aggressive tumor composed of atypical, neoplastic melanocytes. "The transcription levels of RhoBTB2 and RhoT2 were significantly lower in melanoma cells than in MC." (PMID 28404912, 2017).
osteosarcoma (1 paper, 2016). A usually aggressive malignant bone-forming mesenchymal neoplasm, predominantly affecting adolescents and young adults. "Similarly, overexpression of RhoBTB2 in osteosarcoma cells significantly arrested cells at G1 and resulted in apoptosis." (PMID 27314390, 2016).
ovarian carcinoma (1 paper, 2023). A malignant neoplasm originating from the surface ovarian epithelium. "Furthermore, GEPIA database analysis showed that only four genes, PIK3R1, JUNB, RHOBTB2, and SLC25A37, were expressed at low level in ovarian cancer and were correlated positively with YTHDC1." (PMID 37781028, 2023).
stomach carcinomas (1 paper, 2021). "Although RHOBTB2 is frequently deleted in various carcinomas, including breast, lung, and stomach carcinomas, many tumor cells still retain RHOBTB2 expression." (PMID 34074803, 2021).
tumor (21 papers, 2005 to 2024). "There is a consistent association between decreased levels of RHOBTB2 leading to tumor growth in specific tissues, but the mechanisms of tumor suppression are unclear." (PMID 39736890, 2024). "RHOBTB2 is a member of the Rho GTPases subfamily of signaling proteins, known tumor suppressors whose loss of function and decreased expression is associated with cancer onset." (PMID 39736890, 2024). "RHOBTB2, first identified as a tumor suppressor gene, has recently been implicated in a neurodevelopmental disorder." (PMID 39736890, 2024). "RHOBTB2 is responsible for the recruitment of proteins associated with tumor growth for ubiquitination and subsequent degradation by the 26S proteasome." (PMID 39736890, 2024). "Atypical Rho proteins have so far been implicated in multiple activities including tumour suppression (e.g. RhoBTB2), cell transformation and -morphogenesis as well as development (e.g. RhoU and Rnd)." (PMID 34793580, 2021). "Studies examining RHOBTB2 as a tumor suppressor show that decreased levels of RHOBTB2, through variants, epigenetic modifications, or silencing mechanisms, are associated with multiple cancers." (PMID 39736890, 2024). "Precise RHOBTB2 expression levels are key to preventing tumor growth and promoting proper nervous system development and function, however, the role of RHOBTB2 in these processes requires further investigation." (PMID 39736890, 2024). "In both cancer and NDD, RHOBTB2 appears to play a role in the targeted degradation of key proteins related to tumor growth and/or neural development." (PMID 39736890, 2024). "Here, we applied bioinformatics analyses to determine the expression of RHOBTB genes in AML patients based on large-scale gene expressions in copy numbers published online and validate RHOBTB2 as an independent prognostic indicator and a tumor biomarker." (PMID 34074803, 2021). "RHOBTB2 showed notably divergent expression patterns between AML and other tumor types, which led us to further explore the underlying clinical significance." (PMID 34074803, 2021). "We therefore reverse engineered a static ARACNE mutual information network representing the neighbourhood of RND3, RHOC, RHOBTB1 and RHOBTB2 during the tumour implantation time course." (PMID 26132659, 2015). "The exact mechanism by which RHOBTB2 functions as a tumor suppressor is unclear." (PMID 39736890, 2024). "The HSP90 interactors KEAP1 and RHOBTB2/DBC2 act as tumor suppressors." (PMID 26517842, 2015). "However, the extent of tumor growth induced by RHOBTB2 downregulation and whether RHOBTB2 acts in a tissue-specific manner remains unknown." (PMID 39736890, 2024). "Furthermore, although a few proteins associated with tumor growth have been identified as substrates of the RHOBTB2-Cul3/Rbx1 complex, the exact mechanisms by which RHOBTB2 functions as a tumor suppressor remain unclear." (PMID 39736890, 2024). "KALRN, MCF2/Dbl, NGEF/EPHEXIN, ARHGEF7/βPix/COOL-1, CDC42EP2, DOCK9, NET1, TIAM2, ABR, PLEKHG5, RhoBTB2 and PREX1 were identified as being increased at the tumour rim." (PMID 33256106, 2020).
cancer (15 papers, 2005 to 2025). A tumor composed of atypical neoplastic, often pleomorphic cells that invade other tissues. "While RHOBTB2 is linked to cancer onset in cases of decreased expression and neurodevelopmental disorders in potential gain-of-function and loss-of-function scenarios, it remains relatively understudied, with limited information available on its function and disease mechanisms." (PMID 39736890, 2024). "While there are some hypotheses surrounding how the RHOBTB2 protein is involved in cancer and NDD related to variant-specific consequences, the mechanism by which it contributes to these pathologies remains unknown." (PMID 39736890, 2024). "Importantly, we found that loss of RhoBTB2 expression is correlated with loss of CXCL14 expression in HNSC cancer cell lines, and that expression of the chemokine is rescued by re-expression of RhoBTB2." (PMID 28219369, 2017). "Lastly, there is a need for further in vivo studies to identify new treatment avenues for both cancer and DEE, as well as paroxysmal movement disorders associated with RHOBTB2-related disorders." (PMID 39736890, 2024). "RHOBTB2, also known as DBC2, is an important tumor suppressor gene related to various carcinomas, including those of the breast, bladder, colon, liver, lung, and prostate." (PMID 32316112, 2020). "RhoBTB2 can function in cell cycle and apoptosis through ubiquitination and degradation of cancer-related proteins, so we hypothesize that RhoBTB2 plays an intricate and differential role in tumorigenesis depending on target genes with multiple pathways." (PMID 34074803, 2021). "RHOBTB2 promoter methylation, normally a rare event, has been found increased and correlated to reduced or abolished expression of the gene in breast and bladder cancers." (PMID 27314390, 2016). "This review will cover an overview of the current understanding of the structure and function of RHOBTB2, followed by an analysis of recent studies highlighting its hypothesized role in cancer and NDD, clinical characteristics, treatment approaches, and current gaps in knowledge." (PMID 39736890, 2024). "A total of 8 cancer genes with an OncoScore above the 90th percentile was identified (TNFRSF10B, TNFRSF10C, TNFRSF10A, TNFRSF10D, LZTS1, NKX3-1, BNIP3L and RHOBTB2; OncoScore range: 71.4–86.3)." (PMID 28387367, 2017). "Impaired degradation of RHOBTB2 was not reported in other cancer cell line studies and could indicate alternative cell or tissue-specific mechanisms." (PMID 39736890, 2024).
neurodevelopmental disorder (2 papers, 2023 to 2024). A behavioral and cognitive disorder with onset during the developmental period that involves impaired or aberrant development of intellectual, motor, or social functions. "This review provides an overview of the current knowledge of RHOBTB2 function, with an emphasis on its association with neurodevelopmental disorders through an analysis of preclinical studies and case reports that link individual variants with clinical features." (PMID 39736890, 2024). "Focusing on understudied genes such as RHOBTB2 exemplifies how deeper insights into monogenic disorders could provide answers for individuals affected by rare neurodevelopmental disorders and for those exploring novel precision oncology treatments." (PMID 39736890, 2024).
RHOBTB2 also shares sentences with these, for which no sentence is quoted: developmental delay (4 papers); autism (2); infection (2); lung carcinoma (2); microcephaly (2); Acute encephalopathy (1); acute myeloid leukemia (1); Alzheimer disease (1); Arthritis (1); Ataxia (1); bladder (1); bladder cancer (1); Bovine mastitis (1); Dravet syndrome (1); Dyskinesia (1); Dystonia (1); entropion (1); Hypotonia (1); invasive ductal breast carcinoma (1); Lyme disease (1); Macrocephaly (1); malaria (1); neurological disorders (1); non-small cell lung carcinoma (1); nutritional deficiency (1); prostate tumour (1); schizophrenia (1).